HLA-DMB (major histocompatibility complex, class II, DM beta)
Diseases named in the same sentence as HLA-DMB in open-access papers (continued):
Sharing a sentence is not in itself a finding about the gene and the disease.
endometrial carcinoma (1 paper, 2024). A malignant tumor arising from the epithelium that lines the cavity of the uterine body. "Gene Ontology (GO) analysis and Gene Set Enrichment Analysis (GSEA) were employed to explore the signaling pathways associated with HLA-DMB in endometrial cancer." (PMID 39917362, 2024). "Furthermore, in endometrial cancer, elevated levels of HLA-DMB are associated with higher immune infiltration scores and are closely related to various immune-enhancing factors." (PMID 39917362, 2024). "In endometrial cancer, HLA-DMB expression was primarily associated with wound healing, interferon-gamma dominant, inflammatory, and lymphocyte-depleted molecular subtypes, but less so with immunologically quiet and transforming growth factor-beta dominant subtypes." (PMID 39917362, 2024). "However, the role of HLA-DMB in endometrial carcinoma and the underlying mechanisms remain unclear, and its function in the tumor immune microenvironment has yet to be explored." (PMID 39917362, 2024). "It was found that HLA-DMB is frequently genetically altered in endometrial carcinoma, particularly in mixed endometrioid carcinoma." (PMID 39917362, 2024). "We identified HLA-DMB as a promising biomarker for endometrial cancer patients and its involvement in anti-tumor immune responses." (PMID 39917362, 2024). "The GEPIA2 database was employed to confirm the higher expression of HLA-DMB mRNA in UCEC compared to normal tissues, and the relationship between HLA-DMB expression and the stage of endometrial cancer was analyzed." (PMID 39917362, 2024). "By analyzing the potential value of HLA-DMB in the diagnosis and treatment of endometrial cancer, we found that it can improve patient survival rates, effectively reducing overall medical costs and providing long-term economic benefits." (PMID 39917362, 2024). "Comprehensive elucidation of these aspects will contribute significantly to our understanding of the potential therapeutic applications and immune-related dynamics of HLA-DMB in the context of endometrial cancer." (PMID 39917362, 2024). "To further investigate the role of HLA-DMB in endometrial cancer, we verified the high expression of the HLA-DMB gene and protein in the endometrium." (PMID 39917362, 2024). "Further analysis revealed that the high expression group of HLA-DMB in endometrial cancer had improved overall survival (OS) and disease-free survival (DFS)." (PMID 39917362, 2024). "In this study, we analyze the role of the HLA-DMB gene in endometrial cancer using the database, aiming to identify valuable predictive biomarkers for endometrial cancer and provide direction for its immunotherapy and targeted therapy." (PMID 39917362, 2024). "The results indicated that HLA-DMB was differentially expressed across various cancers, particularly in endometrial cancer." (PMID 39917362, 2024). "In conclusion, HLA-DMB testing demonstrates significant potential value in the clinical diagnosis and treatment of endometrial cancer, as evidenced by its favorable cost-benefit ratio." (PMID 39917362, 2024). "We analyzed the role of HLA-DMB in the immune microenvironment of endometrial cancer and found that the high expression group exhibited higher immune infiltration scores and was positively correlated with various immune cells, particularly monocytes." (PMID 39917362, 2024). "Additionally, the expression of HLA-DMB in endometrial carcinoma was examined in the GEPIA2 database, along with its relationship to prognosis." (PMID 39917362, 2024). "Furthermore, through drug sensitivity analysis, we found that the drugs closely related to the HLA-DMB gene include cisplatin, dexamethasone, and ethinylestradiol, offering a new perspective for the treatment of endometrial cancer." (PMID 39917362, 2024).
endometrial carcinoma (continued). "To identify chemicals related to HLA-DMB and provide insights for the treatment of endometrial cancer, we retrieved data from the Comparative Toxicogenomics Database (CTD) and found three substances associated with HLA-DMB: cisplatin, dexamethasone, and ethinyl estradiol." (PMID 39917362, 2024). "It suggests that HLA-DMB may serve as a promising biomarker for predicting survival in endometrial cancer." (PMID 39917362, 2024). "Notably, high expression of HLA-DMB predicted better clinical outcomes in endometrial cancer." (PMID 39917362, 2024). "Univariate COX regression analysis was performed to identify prognostic factors for endometrial carcinoma (EC), and a multivariate COX proportional hazards regression model was used to confirm that HLA-DMB can serve as an independent prognostic factor for EC." (PMID 39917362, 2024). "In the present study, HLA-DMB, as part of the MHC class II complex presenting antigens, demonstrates significant tumor-suppressive effects in endometrial cancer." (PMID 39917362, 2024). "Immunohistochemical results for HLA-DMB in endometrial cancer patients and normal human endometrial tissues were obtained from the HPA database, revealing that HLA-DMB protein levels were elevated in endometrial cancer." (PMID 39917362, 2024). "Most notably, although our analysis has convincingly shown that high expression levels of HLA-DMB are prevalent in endometrial cancer and are predictive of favorable survival outcomes for patients, the precise mechanisms by which HLA-DMB influences endometrial cancer remain inadequately understood." (PMID 39917362, 2024).
endometrioid carcinoma (1 paper, 2024). "Additionally, we found that uterine mixed endometrioid carcinoma was most prone to HLA-DMB mutations, followed by endometrial serous carcinoma, which primarily exhibited amplification mutations, and finally endometrioid carcinoma." (PMID 39917362, 2024).
epilepsy (1 paper, 2023). A brain disorder characterized by episodes of abnormally increased neuronal discharge resulting in transient episodes of sensory or motor neurological dysfunction, or psychic dysfunction. "No studies in the same field have confirmed the role of SPOCK2, CTSZ and HLA-DMB in epilepsy or stress cardiomyopathy." (PMID 36776884, 2023). "Validation of epilepsy and stress cardiomyopathy co-expressed genes at the single-cell level revealed that ALDOA, CTSZ, ERBBS, HLA-DMB and other genes were validated as double disease significant co-expression genes." (PMID 36776884, 2023).
glioma (1 paper, 2024). A benign or malignant brain and spinal cord tumor that arises from glial cells (astrocytes, oligodendrocytes, ependymal cells). "The genes analyzed included HLA‐DQA1, HLA‐DQB1, HLA‐DMB, LY86, MS4A7, FOLR2, and MS4A4A in glioma patients." (PMID 38997808, 2024).
infectious mononucleosis (1 paper, 2021). A condition characterized by an increase in mononuclear white blood cells and swollen lymph nodes, which is usually caused by infection with the Epstein-Barr virus. "Moreover, HLA-DMB, GADD45A, and ISG15 are reported to be involved in Epstein–Barr virus infection, one of the most common human viruses in the world, causing infectious mononucleosis and other illnesses." (PMID 34442377, 2021).
leukemia (1 paper, 2022). A malignant (clonal) hematologic disorder, involving hematopoietic stem cells and characterized by the presence of primitive or atypical myeloid or lymphoid cells in the bone marrow and the blood. "Importantly, some of these genes have already been reported in relation to CML (e.g., AURKB, AZU1, HLA-B, HLA-DMB, PF4) and others have been found to play important roles in different leukemias (e.g., CDCA3, RPL18A, PRG3, TLX3)." (PMID 35008420, 2022).
osteosarcoma (1 paper, 2021). A usually aggressive malignant bone-forming mesenchymal neoplasm, predominantly affecting adolescents and young adults. "Hence, I have compared the prognostic gene set for osteosarcoma, Cox univariate and multivariate analysis showed that BACE2, ING2 ALOX5AP, HLA-DMB, HLA-DRA, and SPINT2 were not the independent prognostic factors for osteosarcoma." (PMID 33520450, 2021).
periodontitis (1 paper, 2025). An acute or chronic inflammatory process that affects the tissues that surround and support the teeth. "In conclusion, we have revealed the diagnostic value of HLA-DMB in periodontitis for the first time, combining DNA methylation with transcriptome data." (PMID 40267082, 2025). "To further confirm the diagnostic value of HLA-DMB for periodontitis patients, we performed ROC analysis in both GSE43525 and GSE16134 datasets." (PMID 40267082, 2025). "HLA-DMB was a diagnostic marker for periodontitis (GSE43525 AUC=0.777 and GSE16134 AUC=0.783)." (PMID 40267082, 2025). "Meanwhile, combining ROC results and clinical validation of HLA-DMB, it showed great potential in distinguishing periodontitis samples from normal samples, thereby HLA-DMB was a novel detection target in diagnosing periodontitis." (PMID 40267082, 2025). "Neutrophils showed a higher infiltration proportion in highly HLA-DMB expressed periodontitis samples." (PMID 40267082, 2025). "Meanwhile, the role of HLA-DMB in periodontitis is probably modified by the downregulated methyltransferase DNMT3B, leading to attenuated expression-inhibition and higher HLA-DMBexpression, which jointly contributed to the progression of periodontitis." (PMID 40267082, 2025). "In our future study, it is imperative to further decipher the functional pathways of HLA-DMB, thereby to develop novel targeted prevention and treatment strategy for periodontitis patients." (PMID 40267082, 2025). "Significantly higher HLA-DMB expression was noticed in PMNs of periodontitis, which probably contributed to the development of periodontitis." (PMID 40267082, 2025). "Our findings are conducive to giving deepen insights into the epigenetic modification and clinical application of HLA-DMB in periodontitis." (PMID 40267082, 2025). "Next, we found that the higher expression of HLA-DMB in periodontitis PMN was probably affected by the methylation modification of DNMT3B, due to the significant correlation between them." (PMID 40267082, 2025). "All periodontitis samples were divided into the high and the low expression group, according to the median HLA-DMB expression." (PMID 40267082, 2025). "Subsequently, HLA-DMB related immune landscape in periodontitis was analyzed based on GSE10334 cohort." (PMID 40267082, 2025). "After joint analysis, we noticed that the significant association between DEG HLA-DMB and differential methyltransferase DNMT3B in periodontitis." (PMID 40267082, 2025). "The results indicated that compared to control samples, the mRNA and protein levels of HLA-DMB were both significantly elevated in periodontitis specimens (p <0.001), in line with the data basing on public database." (PMID 40267082, 2025). "Although the crucial potential of HLA-DMB in periodontitis has been uncovered, there are still several limitations in this present work." (PMID 40267082, 2025). "Moreover, considering the key contribution of HLA-DMB in periodontitis PMN, we found that neutrophils and other 8 types of immune cells were significantly differentially infiltrated between high and low expression periodontitis samples." (PMID 40267082, 2025). "Significantly higher HLA-DMB expression and its close correlation with methyltransferase DNMT3B were observed in periodontitis samples, and HLA-DMB was a promising diagnostic marker for periodontitis patients." (PMID 40267082, 2025). "After integrating DNA methylation with transcriptome profiles, GRASP, HLA-DMB, HLA-DMA, CAB39, NCOA2 and TLE4 were identified as candidate genes in periodontitis PMNs." (PMID 40267082, 2025). "Our results showed that DNMT3B was significantly negatively correlated with GRASP, HLA-DMB, HLA-DMA, CAB39, and TLE4, implying the predominant role of DNMT3B in periodontitis." (PMID 40267082, 2025). "Accordingly, the role of HLA-DMB should be related to neutrophils/ PMN in periodontitis, although the exact mechanism between them was not clear at present." (PMID 40267082, 2025).
septic shock (1 paper, 2013). Shock caused by infection; frequently caused by gram negative bacteria, although some cases have been caused by other bacteria, viruses, fungi, and protozoa; characterized by fever, chills, tachycardia, tachypnea, and hypotension. "In a cohort of 93 septic shock patients alive three days after shock, mHLA-DR was measured by flow cytometry and CD74, HLA-DRA, HLA-DMA, HLA-DMB and CIITA mRNA levels were evaluated in whole blood by qRT-PCR." (PMID 24321376, 2013).
staphylococcus aureus infection (1 paper, 2021). An infectious process in which the bacteria Staphylococcus aureus is present. "The second-ranked pathway (though non-significant) was Staphylococcus aureus infection, represented by DEFA4, C3AR1, and HLA-DMB." (PMID 34442377, 2021).
uterine corpus endometrial carcinoma (1 paper, 2024). A endometrial carcinoma (disease) that involves the body of uterus. "Therefore, we conducted a preliminary exploration of the prognostic value and potential mechanisms of HLA-DMB in uterine corpus endometrial carcinoma (UCEC)." (PMID 39917362, 2024). "However, the expression profile, prognostic significance, and molecular mechanisms of HLA-DMB in uterine corpus endometrial carcinoma (UCEC) remain unclear." (PMID 39917362, 2024).
tumor (22 papers, 2010 to 2024). "HLA-DMB expression was negatively correlated with tumor purity and positively correlated with the infiltration levels of CD4+ T cells, CD8+ T cells, B cells, neutrophils, monocytes, myeloid dendritic cells, NK cells, and mast cells." (PMID 39917362, 2024). "Specifically, further research is imperative to delineate the effects of HLA-DMB on tumor behavior and its role in modulating the immune response." (PMID 39917362, 2024). "The results indicated that HLA-DMB expression was significantly correlated with tumor histological type, histological grade, tumor invasion, and clinical stage." (PMID 39917362, 2024). "In the subgroup analysis, HLA-DMB was significantly down-regulated in patients with higher histological grade (especially G3), serous cancer type, higher depth of tumor invasion (≥50%), and advanced clinical stage (stage III and IV)." (PMID 39917362, 2024). "The differential expression of HLA-DMB was analyzed in 554 tumor samples and 35 normal samples obtained from the TCGA database." (PMID 39917362, 2024). "As a tumor-associated gene, Human leukocyte antigen-DMB (HLA-DMB) is embedded in intracellular vesicles." (PMID 36253800, 2022). "Additionally, we analyzed the relationship between HLA-DMB expression and clinical features, including body mass index (BMI), age, histological type, histological grade, tumor invasion, and clinical stage." (PMID 39917362, 2024). "Interestingly, our study showed strong association of five HLA genes (including HLA-DMA, HLA-DMB, HLA-DOA, HLA-DRB6 and HLA-E) with delayed tumor recurrence in both cohorts." (PMID 34834481, 2021). "The results indicated an increase in MS4A4A, HLA‐DMB, LY86, MS4A7, and FOLR2 expression in GBM tumor samples compared to normal tissue samples (n = 706)." (PMID 38997808, 2024). "The results showed a significant correlation between CHST11 and certain tumor immunostimulators (CD28, IL2RA, and TNFSF13B), tumor immunoinhibitors (CD96 and LGALS9), and MHC proteins (HLA-DRA and HLA-DMB)." (PMID 38565604, 2024). "Meanwhile, HLA-DPA1, HLA-DQA1, HLA-DPB1 and HLA-DMB belong to MHC class II, one of the most important components in tumor-immune interactions." (PMID 33066530, 2020). "Increased expression of MHC class II genes CD74, HLA-DMB, and HLA-DQA1 indicate higher tumour antigen processing by the antigen presenting cells in clusters III and IV." (PMID 29050337, 2017). "It is worth noting that the interaction between HLA‐II molecules (such as HLA‐DRA, HLA‐DRB1, HLA‐DRB5, HLA‐DQB1, HLA‐DPB1, HLA‐DPA1, HLA‐DMB and HLA‐DMA) and the receptor CD4 was exclusively detected in the cell communication between malignant cells from single‐primary tumours and Tregs." (PMID 39601163, 2024). "HLA-DMB is an essential component of MHC complex synthesis, and the expression of this gene is prominently positively correlated with the level of infiltration of tumor-infiltrating CD8+ T cells." (PMID 36245844, 2022). "Human MHC class II molecules (HLA-DMB, HLA-DMA, HLA-DRA, HLA-DOA) in the top 30 DMRs, which could attract inflammatory tumour-specific CD4+ T cells and dampen CD8+ T cell antitumour reactivity, were found to be hypomethylated in all CLL patients in our study." (PMID 36712882, 2022). "When comparing our gene expression analyses and genetic analyses, the cancer genes HLA-DPA1, HLA-DMB, DNAJA4, LY86, HCLS1, GABBR1, NUDT16 showed upregulation in tumor tissue compared to cell subpopulations and are located in chromosomal regions that showed losses in GSC and CD133pos./CD15pos. cells." (PMID 32634135, 2020). "Furthermore, the HLA-DMA and HLA-DMB genes are expressed at high relative levels, similar to those for CDH1 (epithelial cells) and CD68 (macrophages), suggesting that they may be expressed by these cell types within the tumor." (PMID 36497170, 2022).
cancer (14 papers, 2016 to 2025). A tumor composed of atypical neoplastic, often pleomorphic cells that invade other tissues. "The IDEGs (SLPI, IAPP, NPY, ISG15, PLA2G2A, and HLA-DMB) in the predictive PCa risk model constructed in the present study play an important regulatory role in cancer." (PMID 36774376, 2023). "The differential expression of HLA-DMB across various cancers, along with immune infiltration analysis, was conducted using the TIMER2.0 database." (PMID 39917362, 2024). "In this study, we utilized TCGA and other databases to analyze the differential expression of HLA-DMB across 33 types of cancer and adjacent tissues." (PMID 39917362, 2024). "First, the expression level of HLA-DMB in pan-cancer was analyzed using the TIMER2.0 database." (PMID 39917362, 2024). "The immune histochemical sections of the HPA database showed that the protein expression of SLPI, DES, IAPP, NPY, ISG15 and HLA-DMB in normal tissue was higher than that in cancer tissue, while the protein expression of PLA2G2A in normal tissue was lower than that in cancer tissue." (PMID 36774376, 2023). "In most of the cancers, there was a significant correlation between UBE2C gene expression and HLA‐DMB, HLA‐DOA, HLA‐DPA1, HLA‐PDB1, HLA‐DRA, and HLA‐E." (PMID 38577722, 2024). "Among them, HLA-DMB, HLA-DRA, IL12A, and IL12B, whose determinant role in cancer outcome as immune adjuvants has already been published, are found in the top 500 TG2 positively correlating genes." (PMID 35725560, 2022). "HLA-DMB, the beta chain of the non-classical MHC class II protein HLA-DM, has been implicated in the progression of various cancers." (PMID 39917362, 2024).
HLA-DMB also shares sentences with these, for which no sentence is quoted: infection (2 papers); lung adenocarcinoma (2); Allergy (1); B-cell lymphoma (1); B-cell neoplasm (1); bacterial infection (1); cardiomyopathy (1); celiac disease (1); cervical squamous cell carcinoma (1); cervix tumors (1); colon cancer (1); colorectal cancer (1); cutaneous melanoma (1); dementia (1); diffuse large B-cell lymphoma (1); Epstein-Barr virus infection (1); esophageal squamous cell carcinoma (1); germ cell tumor (1); hypopharyngeal cancer (1); lung disease (1); lymphoma (1); mesothelioma (1); multiple sclerosis (1); neuroblastoma (1); osteoarthritis (1); psoriasis (1); renal cell carcinoma (1); stress cardiomyopathy (1); Stroke (1); systemic lupus erythematosus (1).
A further 2 diseases each share a sentence with HLA-DMB in 1 paper.